ENSG00000252274
Synonyms: LOC124904115
Gene: Small Cajal body-specific RNA gene on chromosome 17 (72,818,836 to 72,818,972, reverse strand). Ensembl gene ENSG00000252274.
Gene Ontology:
Biological process: RNA processing
Cellular component: Cajal body; nucleolus